BRCA1 (BRCA1 DNA repair associated)
Diseases named in the same sentence as BRCA1 in open-access papers (continued):
Sharing a sentence is not in itself a finding about the gene and the disease.
tumor (continued). "The concept of BRCAness or HRD phenotype, defined as double-strand break repair deficiency in the absence of a BRCA1/2 variant, is of growing interest across tumor types, including PDAC." (PMID 37296917, 2023). "Additionally, the murine homologue of p.BRCA1-Leu1407Pro has been shown to promote tumor formation in mice." (PMID 37917606, 2023). "CCNE1 amplification rates were significantly lower in BRCA1/2 mutated tumours compared to BRCA-wildtype, although the difference did not remain significant after multiple testing corrections." (PMID 37474499, 2023). "According the guidelines, at least 76.3% of patients in this study would receive two tests because they are negative for a germline variant and would need a subsequent tumor test to identify somatic BRCA1/2 variants." (PMID 36922847, 2023). "In women who do not carry a germline pathogenic or likely pathogenic BRCA1/2 variant, somatic tumor testing should be performed." (PMID 37181681, 2023). "In addition, higher H3K27ac levels were detected on genes related to signaling of interleukins in BRCA1-null tumor cells." (PMID 37063431, 2023). "Moreover, tumor testing, at least for the BRCA1 and BRCA2 genes, is recommended for all women who test negative for germline pathogenic variants." (PMID 37241036, 2023). "Since ACC1 participates in the first step of fatty acid biosynthesis and the up-regulation of such a process is required for carcinogenesis, BRCA1 might act as a tumour suppressor." (PMID 37514027, 2023). "This increase is largely owing to a 3.8-fold elevation in SBS13 mutations (P < 0.0001 by Mann–Whitney U test), whereas SBS2 mutations occurred at similar levels between BRCA1/2-proficient and BRCA1/2-deficient tumors (median values of 151 and 142 SBS2 mutations per tumor), respectively." (PMID 37532520, 2023). "Many hypotheses have been formulated to reconcile the conflicting observations surrounding BRCA1’s dual roles in general cellular function and tissue-specific tumor suppressor activity." (PMID 37762577, 2023). "The tumor suppressor genes BRCA1 and BRCA2 also play an important role." (PMID 37760950, 2023). "Sensitivity to either GSK3326595 or niraparib did not correlate with BRCA1 or BRCA2 mutation status or tumor type." (PMID 37596538, 2023). "From a total of 6830 tumor samples from 6527 individual patients that underwent tumor DNA sequencing, 584 unique tumor variants were identified in the gene list of interest (ATM, BRCA1, BRCA2, MLH1, MSH1, MSH6, PALB2 and PMS2) from 503 unique tumor samples/patients during the study period." (PMID 36261688, 2023). "Notably, defects in the homologous recombination repair (HRR) pathway, regulated by BRCA1 and BRCA2 proteins, are linked to multiple tumor types, including breast, ovarian, and gastric cancers." (PMID 37958290, 2023). "While many potential substrates have been posited for this activity, a thought-provoking revelation emerges: the E3 ligase function of BRCA1, as demonstrated in animal models, is not indispensably linked to its tumor suppression role." (PMID 37762577, 2023). "However, tumor cells with other mechanisms of PARPi resistance, such as BRCA1 or BRCA2 restoration, remain resistant to Polθ inhibitors." (PMID 36652375, 2023). "Based on these mechanisms, BRCA1/2 gene deficiency causing and PARP inhibition may synergistically prompt death in tumor cells, known as synthetic lethality." (PMID 37152924, 2023).
tumor (continued). "We first assessed the effect of ART558, alone and in combination with IR, in three tumor cell lines that do not harbor mutations in BRCA-1 or BRCA-2 genes: HCT116 (colorectal), H460 (lung), and T24 (bladder)." (PMID 36689546, 2023). "Patients with BRCA1- and BRCA2-mutated tumors treated with PARPis often have dramatic treatment responses as the synthetic lethality induced by the PARPi leads to cell death within the tumor." (PMID 36968138, 2023). "PARP inhibitors are synthetically lethal in tumours with homologous recombination deficiencies (HRD), in particular in tumours with either a germline or somatic mutation in the breast cancer type 1/2 susceptibility gene (BRCA1/2)." (PMID 37474720, 2023). "Therefore, we selected patients with a proven hypermethylated BRCA1 promoter in their tumor to increase the chance of finding the SNV." (PMID 36112334, 2023). "Subsequent germline BRCA1/2 testing is then requested for patients with a positive tumour BRCA1/2 test result, thereby determining whether the pathogenic/likely pathogenic variant is constitutional (i.e., germline) or somatically acquired (i.e., tumour-only)." (PMID 38201604, 2023). "Thus, we identified a novel NORE1A/BRCA1 tumor suppressor complex and identified a new link between Her2 and BRCA1 via NORE1A." (PMID 37627161, 2023). "However, we suggest the complete BRCA1 deletion for this sample to be due to a possible low tumor cell percent." (PMID 38068953, 2023). "The investigation found that lack of BRCA1 expression was associated with poor tumor differentiation, advanced-stage disease, and decreased overall survival (OS) compared to patients with BRCA1 expression in their GC." (PMID 36497436, 2022). "BRCA1 is a well-known tumor suppressor in humans that is evolutionarily conserved also in plants." (PMID 36578335, 2022). "First, some information is missing from the SEER database, such as BRCA1/2 mutation, Ki67, HER2 status before 2010, and tumor progression, which may affect the performance of the model." (PMID 36338687, 2022). "Importantly, we observed significantly enriched CD8+ T cells in BRCA1 carriers (χ2 test p = 4.07 × 10−8), suggesting an early role for the adaptive immune system prior to tumor initiation." (PMID 36076202, 2022). "Since the tumor suppressive effect of HspBP1 is dependent on BRCA1, we predicted that HspBP1 might directly regulate BRCA1 function." (PMID 35387978, 2022). "Interestingly, in other BRCA1-methylated PDX tumours, BRCA1 re-expression was determined by de novo intrachromosomal genomic rearrangements through which BRCA1 transcription is placed under the control of a heterologous promoter." (PMID 35681784, 2022). "It should be noted that similar but different phenotypes of SBS3 may arise dependent on the underlying cause and even tumor type, e.g., BRCA2 and PALB2 inactivation lead to larger deletions when compared to BRCA1- and RAD51-related HRD." (PMID 36077694, 2022). "It is possible that the tumor suppression by BRCA1 may be in part mediated by ZNF148 activation as a result of MYC downregulation." (PMID 36207293, 2022). "Furthermore, germline mutations in BRCA1/2 HR pathway interaction partners, PALB2 and RAD51C, were also shown to confer a tumor mutation signature enriched for HR deficiency in four cases of GC." (PMID 36497436, 2022). "The other tumor (M232) only showed LOH at the BRCA1 and BRCA2 loci without loss of function in the other allele." (PMID 35662281, 2022). "Furthermore, the effect of high glucose, as compared to physiological concentrations, on the tumor suppressive role of BRCA1 was investigated." (PMID 35432218, 2022). "It was reported that PRKCDBP could interact with BRCA1 protein and be involved in DNA damage response and participate in the BRCA1-mediated tumor suppressor pathway." (PMID 35224960, 2022).
tumor (continued). "As the tumor progressed rapidly, genetic testing of tumor showed no mutation in BRCA1 and BRCA2 while UGT1AI*6, UGT1A1*28, UGT1A1-3156 gene polymorphism was detected." (PMID 36741732, 2022). "Accordingly, we see that Brca1-deficient tumor cells that acquire senescence defects are nonresponsive to the chemotherapy/ICB combination." (PMID 35082152, 2022). "Although this may have influenced CHORD results, this cannot explain the HRP score for the BRCA1/2-like classifier, which only requires tumor tissue." (PMID 35662281, 2022). "The transcriptional mechanism of Brca1 has also been well documented in tumor tissues." (PMID 36430332, 2022). "Despite the advances made in vitro to decipher BRCA1 cellular functions, the importance of BRCA1 mutations in the clinical setting and the rapid escalation of the clinical use of PARP inhibitors, a deeper understanding of HGSC tumor molecular phenotypes is still necessary." (PMID 35292711, 2022). "Hierarchical clustering and PC analysis for the 10,000 most variable CpGs showed that recurrent tumors continued to cluster most closely with the matched primary tumor from the same patient rather than by primary, recurrent or BRCA1/2 mutation status." (PMID 35883104, 2022). "It is possible that partially platinum sensitive patients may have a different proportion of women with tumours who are sensitive due to the methylation of HR genes, such as BRCA1, and for whom a demethylating agent may have an adverse effect." (PMID 35326684, 2022). "PARP inhibitors are a class of therapeutic agents that have been shown to be effective for the treatment of malignancies, including tumours associated with BRCA1/2 mutations or without BRCA mutations but with homologous recombination deficiencies." (PMID 34795408, 2022). "The hypothesis suggested is that BRCA1 (185delAG) tumour cells produce a RING-less BRCA1 protein; this structure may lead to PARPi resistance through its residual activity by activating RAD51." (PMID 35681784, 2022). "However, new studies imply that these substances are similarly active in tumours harbouring wild type BRCA1/2." (PMID 35964058, 2022). "As expected, mutations in the AR and DNA repair genes included in our panel were the most common ones, in particular, the ATM and BRCA1/BRCA2 genes, and they seemed to drive high tumor mutation load and rapid polymetastatic spread after the first oligorecurrence treated with SBRT." (PMID 35740343, 2022). "The tumor suppressor BRCA1 is initially discovered as an early-onset breast cancer susceptibility gene and its mutation predisposes individuals to early onset of disparate familial diseases, leading to not only breast and ovarian cancers, but also the Fanconi anemia (FA)." (PMID 35246238, 2022). "Conditions mimicking the tumor microenvironment, such as hypoxia, also silenced Brca1 expression." (PMID 36430332, 2022). "The results of our study showed that, as is the case for non-hereditary BC, smaller tumor size was associated with improved OS in pT1N0M0 BRCA1/2-associated BC patients." (PMID 35507134, 2022). "In TOPARP-B, patients with tumours harbouring homozygous BRCA2 deletions demonstrated a superior median rPFS of 16.4 months vs. 5.6 months for germline BRCA1/2 mutations and 8.2 months for BRCA1/2 somatic mutations." (PMID 36497408, 2022). "Interestingly, loss of heterozygosity of BRCA1 was observed in only 29% of post-NACT tumour tissues, whereas it was found in 82% of BRCA1 tumour tissues in chemonaive patients." (PMID 35957909, 2022). "Importantly, we report a prognostic role of a proliferative tumor-cell subpopulation, which associates with enhanced spatial tumor-immune interactions by CD8+ and CD4 + T-cells in the BRCA1/2mut tumors." (PMID 35149709, 2022).
tumor (continued). "Despite the fact that previous studies demonstrated that tumors harboring BRCA1/2 dysfunction and treated with PARPi could increase tumor immunogenicity, therefore sensitizing tumor cells to anti-CTLA4 agents, the whole process remains understudied." (PMID 36533080, 2022). "Accordingly, BRCA1 status and tumor hypoxia should be considered as key clinical parameters which may affect the therapeutic efficacy of the HDAC inhibitors." (PMID 35870078, 2022). "In the nucleus, BAP1 binds to BRCA1 and enhances its tumor suppressive activity." (PMID 35425712, 2022). "Moreover, downregulation of EZH2 or BRCA1 sensitized A2780/DDP cells to cisplatin, which contradicts BRCA1’s tumor-suppressing role but is in line with the concept that its upregulation is associated with DNA repair-mediated resistance to cisplatin." (PMID 36230683, 2022). "BRCA1 plays a vital role in DNA repair, transcriptional regulation and tumor suppressor functions." (PMID 34643844, 2022). "Patients with tumor somatic mutations did not have significantly different OS compared with those with wild-type BRCA1/2 (HR = 0.67 (95% CI = 0.23–1.93))." (PMID 35909902, 2022). "While this same study noted three cases of GC with a germline BRCA1 mutation, the tumor mutation signatures were not reported." (PMID 36497436, 2022). "The BRCA1/2-like classifier missed four and CHORD one bi-allelic BRCA deficient tumor(s)." (PMID 35662281, 2022). "Furthermore, a reduction in BRCA1 level has been shown to increase activation of CD8+ tumor-infiltrating lymphocytes." (PMID 35118379, 2022). "BRCA1/2 form protein complexes with known tumor suppressors including RAD51, BARD1 and PALB2." (PMID 35251494, 2022). "Similarly, most patients had multiple subclonal BRCA1/2 reversion events, likely representing convergent evolution in the context of acquired tumor resistance through multiple subclones." (PMID 36470901, 2022). "In addition, pamiparib induced significant tumour regression in a BRCA1-mutant breast cancer xenograft model with 16-fold higher efficacy compared with olaparib." (PMID 34795408, 2022). "The loss of BRCA1 facilitated the enrichment of enhancers and the transcriptional upregulation of key genes in inflammatory pathways, DNA sensing pathways and IFN responses, committing tumour cells to an inflammatory state that promotes TIL recruitment." (PMID 36159999, 2022). "One of these is the small subclonal tumour cells that do not have the BRCA1/2 mutations, and after starting treatment, become the main clone that does not respond to targeted treatment." (PMID 35545786, 2022). "If this proves to be the case, it may be possible to design vaccines based on candidate neopeptides predicted to occur upon reversion and to use these to prevent or delay BRCA1/2 revertant tumour outgrowth." (PMID 35892198, 2022). "This context may be conducive to treatment with PARP inhibitors that have been shown to act by synthetic lethality in tumor cells with impaired BRCA1/2 complex." (PMID 35978432, 2022). "Genetic risk evaluation showed that this patient did not have a BRCA1/2 mutation in germline or tumor DNA." (PMID 35907904, 2022). "Moreover, OCs can be divided in type I (low-grade tumor with BRAF and KRAS mutations) or type II (high-grade tumor with a variety of mutations including HOX, PTEN, KRAS, AKT1, BRCA1/2 genes) and various dysregulated mechanisms underlying the pathology." (PMID 36191006, 2022). "However, several BRCA1-methylated PDX tumours acquired therapy resistance via re-expression of BRCA1 thanks to the loss of the BRCA1 promoter methylation." (PMID 35681784, 2022).
tumor (continued). "To assess the tumor mutational burden of BRCA1-positive and -negative samples, we compared coding-region non-synonymous variant count per sample from each group within the same database." (PMID 36298462, 2022). "Given that BRCA1 and BRCA2 (BRCA1/2) deficiency is a common mutation in BC and confers impaired homologous recombination repair (HRR) phenotype to tumor cells, poly ADP-ribose polymerase (PARP) inhibitors (PARPi) should be utilized as an example of precision medicine targeting DNA damage response." (PMID 36046364, 2022). "Inhibition of efficient PARP1/2-dependent DDR is fatal for tumor cells with homologous recombination deficiencies (HRD), especially defects in breast cancer type 1 susceptibility protein 1 or 2 (BRCA1/2)-dependent pathway, while allowing healthy cells to survive." (PMID 36533080, 2022). "Actually, three of four large intragenic variants were detected by tumor genotyping and the only variant that was not identified, was the deletion of promotor region and exons 1 and 2 of the BRCA1 gene." (PMID 35326583, 2022). "The proliferation of landed tumor cells might gradually be triggered by other types of signaling pathways in low BRCA1 expression patients." (PMID 34996912, 2022). "Our results suggest that patients may benefit from post-test genetic counselling and/or educational resources following BRCA1/2 tumour testing in order to better understand and recall their results." (PMID 35418215, 2022). "Interestingly, the deletion of 53BP1 in a BRCA1 mutant model restored tumor cells survival following DNA damage treatments, especially following PARPi." (PMID 36553657, 2022). "Third, the aggressive tumor behavior of patients with high BRCA1 expression could be improved by approximately 20% with tamoxifen treatment." (PMID 34996912, 2022). "Furthermore, genetic inactivation of POLQ is synthetic lethal with HR defects caused by either BRCA1, BRCA2, ATM, RAD51C or FANCD2 defects and tumour overexpression of POLQ correlates with HRD status and a poor clinical outcome." (PMID 35567571, 2022). "Given the benefits of targeted therapy with a PARPi among HGSOC patients with a BRCA1/2 PV, it is possible that receiving positive BRCA1/2 tumour genetic testing result may be perceived as ‘good’ news." (PMID 35418215, 2022). "In addition to BRCA1/2 testing, NCCN and ESMO-ESGO recommend considering somatic tumor testing for PV/LPV in other homologous deficiency (HR) genes as well as the evaluation of HR deficiency when deciding on PARP inhibitor therapy." (PMID 35326583, 2022). "Among the nine tumors with germline BRCA1/2 mutations, one tumor (M248) harbored a germline BRCA1 variant (c.5309G>T p.Gly1770Val) that was not classified as pathogenic in CLINVAR." (PMID 35662281, 2022). "Homologous recombination-deficient HRD-Dup (BRCA1 mutant-like) and HRD-Del (BRCA2 mutant-like) tumours harboured inflammatory signalling and ongoing immunoediting, reflected in loss of HLA diversity and tumour infiltration with highly differentiated dysfunctional CD8+ T cells." (PMID 36517593, 2022). "Moreover, RNF8 utilizes the RING domain, mediating Lys63-linked Ub chains, which is required for DNA double-strand break (DSB) signaling and the downstream BRCA1 tumor suppressor recruitment or lung cancer cell proliferation." (PMID 35874839, 2022). "However, for assessing the occurrence of tumour types that are atypical for the relevant CSGs, for non-BRCA1/BRCA2 MINAS combinations, the number of instances of specific CSG combinations was generally very small." (PMID 34983940, 2022). "Although 40.8% of participants in our study had met with a genetic counsellor prior to completing the study survey, it is unknown whether BRCA1/2 tumour results were available or discussed during their appointment." (PMID 35418215, 2022). "A PV in BRCA1/2 was identified in 23 (30.3%) of HGSOC tumours." (PMID 35418215, 2022).